ABCA1 (ATP binding cassette subfamily A member 1)
Diseases named in the same sentence as ABCA1 in open-access papers (continued):
Sharing a sentence is not in itself a finding about the gene and the disease.
ischemic stroke (continued). "For the ABCA1 (rs1883025) SNP, while the T allele was associated with reduced HDL cholesterol levels, individuals with the T/T genotype in the high-protein intake group exhibited a significantly lower risk of ischemic stroke compared to those in the low-protein intake group." (PMID 40077648, 2025). "Furthermore, in the context of ischemic stroke, the expression of perilipin-2 (Plin2) is upregulated, and the expression of ATP-binding cassette transporter A1 (ABCA1) is downregulated, leading to increased lipid droplet formation and impaired cholesterol clearance in TREM2-deficient microglia." (PMID 40242752, 2025). "Our study does not support a major role for the ABCA1 gene as a risk factor for ischaemic stroke." (PMID 17553166, 2007).
malaria (11 papers, 2017 to 2025). Malaria is a serious and sometimes fatal disease caused by a parasite that commonly infects a certain type of mosquito which feeds on humans. "This study prompted further investigations that identified associations between ABCA1 gene promoter polymorphisms and plasma MV levels in malaria patients." (PMID 39868784, 2025). "Demonstration of a strict correlation between ABCA1 gene promoter polymorphisms and augmented plasma EV levels and disease complications in human malaria patients." (PMID 39113589, 2024). "The authors reported that MV release increased during malaria infection, MV levels positively correlated to disease severity, and ABCA1 promotor genotypes were associated with susceptibility to severe malaria." (PMID 28599650, 2017). "Additionally, there is a correlation between ABCA1 gene promoter polymorphisms and plasma EV levels in malaria patients, suggesting a potential genetic susceptibility to severe disease." (PMID 39113589, 2024). "The importance of ABCA1 in MV-related malaria pathogenesis was further supported by findings from a field study of human patients infected with Plasmodium falciparum, where MV levels in patients with severe and uncomplicated malaria were tested for association with their ABCA1 promoter haplotypes." (PMID 28599650, 2017). "ABCA1 promoter variants associated with increased atherosclerotic burden were found to be associated with decreased MP levels and were more prevalent in patients with uncomplicated malaria, suggesting that these polymorphisms have a protective effect against severe malaria in humans." (PMID 33562440, 2021). "The mutant genotype of the ABCA1 gene promoter was proposed to influence lower MV production during malarial infection, impacting the severity of malaria in humans." (PMID 39868784, 2025). "At the protein level, poly(I:C) decreased Abca1 staining in the Lz but increased staining in Jz, similar to what was found in malaria and ZIKV models." (PMID 35715474, 2022). "Previously, we have demonstrated that malaria in pregnancy (MiP), an important inducer of preterm labor, upregulated term yolk sac P-gp and Abca1 expression." (PMID 32916274, 2020). "Interstingly, a study found that polymorphisms in the human ABCA1 promoter correlate with the severity of the disease, further suggesting a role for ABCA1 in controlling the level of pro-inflammatory EVs during malaria disease." (PMID 32082312, 2020). "Furthermore, ABCA1 promoter variants were associated with increased microvesicle production and a higher risk of developing severe malaria in humans, suggesting that ABCA1 genetic variation may confer susceptibility to the development of malaria and its complications." (PMID 33562440, 2021). "In humans, EV release was considerably lower in patients with uncomplicated malaria/ non-cerebral severe malaria and polymorphisms in the ABCA1 gene, while in patients with CM/multiorgan dysfunction and the wildtype ABCA1 gene, EV release was remarkably higher." (PMID 34801056, 2021). "Changes in ABCA1 and P‐gp in MiP may alter the biodistribution of toxic substances, xenobiotics, nutrients and immunological factors within the fetal compartment and participate in the pathogenesis of malaria‐induced IUGR and PTL." (PMID 32779889, 2020). "Using a mouse model of malaria‐induced IUGR and PTL, we detected increased expression of P‐gp/Abcb1a and Mif chemokine in the yolk sac, and endothelial ABCA1 staining in blood vessels." (PMID 32779889, 2020). "Changes in the expression pattern of yolk sac ABCA1 and P‐gp may alter the biodistribution of toxic substances, xenobiotics, nutrients and immunological factors within the foetal compartment and therefore participate in the pathogenesis of malaria‐induced IUGR and PTL." (PMID 32779889, 2020). "Consistent with the gene expression responses, the levels of ABCA1, P-gp and BCRP protein were significantly reduced in the malaria infected animals, when compared to controls." (PMID 31391498, 2019).
malaria (continued). "Due to the fact that Abca1, Abcb1b and Abcg2 were downregulated in malaria infected pregnancies, the protein expression levels of the correspondent best described ABC transporters, ABCA1, P-gp and BCRP were assessed." (PMID 31391498, 2019).
asthma (10 papers, 2008 to 2026). "The association between ABCA1 function and asthma is still a novel and underdeveloped area." (PMID 28241820, 2017). "This study aimed to explore the expression level of SREBP2 and ATP-binding cassette transporter A1 (ABCA1), and their effects on the development of airway smooth muscle cells (ASMCs) in asthma." (PMID 35037821, 2022). "Studies in utero have shown that maternal famine was associated with higher methylation of IL10, LEP, ABCA1, GNASAS, and MEG3 genes, compared to the same-sex unexposed siblings, potentially increasing risk of asthma later in life." (PMID 32047643, 2019). "Multi-omics data reveal that ABCA1 is upregulated in macrophages during acute exacerbations but downregulated in chronic or severe asthma, suggesting a dual role that may involve extracellular-trap formation." (PMID 41602451, 2026). "In this study, we speculate that SREBP2 is a crucial regulator for asthma and may be involved in asthma by regulating cell motility and the activity of ABCA1." (PMID 35037821, 2022). "Therefore, the present study used TGF-β1 stimulation to prepare ASMCs cell models in vitro to investigate the specific role of SREBP2 in the mechanism of airway remodeling in asthma and the regulation of ABCA1." (PMID 35037821, 2022). "However, in vivo animal experiments are needed in future studies to deeply validate the role of SREBP2 and ABCA1 in asthma." (PMID 35037821, 2022). "It has been reported that the apoA-I/ABCA1 pathway may have a protective effect on asthma, supporting the concept of advancing inhaled apoA-I mimetic peptides to a clinical trial of asthma." (PMID 34064071, 2021). "Several genes such as SERPINE1, GPRC5A, SFN, ABCA1, MKI67, and RRM2 have been found to be downregulated in severe uncontrolled asthma using PBMCs and, therefore, potential biomarkers." (PMID 36294997, 2022). "Therefore, we speculated that SREBP2 might alter cell motility by regulating ABCA1 in asthma." (PMID 35037821, 2022). "However, whether SREBP2 also can modulate the activity of ABCA1 in asthma is unknown." (PMID 35037821, 2022). "Validation of the gene expression in PBMC of locally recruited asthma patients showed that SERPINE1, GPRC5A, SFN, ABCA1, MKI67, and RRM2 were downregulated in severe uncontrolled asthma." (PMID 34088958, 2021). "Furthermore, it is known that when ABCA1 is repressed, excess cholesterol builds up in alveolar cells, damaging surfactant function and increasing the inflammatory response which has been implicated in the pathogenesis of chronic obstructive pulmonary disease (COPD), asthma and other lung diseases." (PMID 32977800, 2020). "SERPINE1, ABCA1, and KRT8 showed higher expression in bronchial biopsies than the pure bronchial epithelium, in moderate and severe asthma, with and without oral steroid use." (PMID 34088958, 2021). "ABCA1 and RRM2 expression were lower in severe asthmatics than nonsevere asthmatics and healthy controls, making them potential biomarkers to differentiate the asthma severity." (PMID 34088958, 2021).
coronary atherosclerosis (10 papers, 2019 to 2024). Atherosclerosis of the coronary vasculature. "Recent studies have shown that some lipid metabolism genes, such as cholesteryl ester transfer protein (CETP) and ATP-binding cassette subfamily A member 1 (ABCA1) may indirectly cause MI by affecting coronary atherosclerosis progression." (PMID 37180972, 2023). "Further, in individuals with coronary atherosclerosis, up-regulated serum miR-93 is positively associated with raising serum cholesterol levels through targeting ATP binding cassette subfamily A member 1 (ABCA1)." (PMID 37076893, 2023). "The second notable finding of the present study is the observation that in obese participants, macrophage ABCA1-CEC is positively associated with coronary atherosclerosis burden quantified by the CAC score, whereas no such association was retrieved in healthy controls." (PMID 31443207, 2019). "This suggests that normal EAT is active for reverse cholesterol transport, and hypermethylation of key cholesterol transport genes, including ABCA1 and ABCG1, may play a role in coronary atherosclerosis." (PMID 34837967, 2021). "Additionally, SP1 may offer protection against coronary atherosclerosis and cardiac remodeling post-myocardial infarction by influencing the gene transcription of PSRC1, ABCA1, SR-BI, and P4Ha1." (PMID 39062521, 2024). "Infusion of CER-001 did not promote regression of coronary atherosclerosis in statin-treated patients with ACS and high plaque burden, which may be due to the strong (50%) downregulation of ABCA1 mRNA and membrane protein expression at higher doses of CER-001." (PMID 33390931, 2020).
lipid metabolism disorder (10 papers, 2017 to 2026). "The search for rare variants (gnomAD frequency less than 1 %) in the ABCA1, ABCG1, ABCG5, ABCG8 and NPC1L1 genes was performed using targeted sequencing data for 169 patients with lipid metabolism disorders." (PMID 42253452, 2026). "The aim of this work was to study the spectrum of rare variants in the cholesterol transporter genes ABCA1, ABCG1, ABCG5, ABCG8 and NPC1L1 that occur in patients with lipid metabolism disorders in the population of the Northwestern region of Russia." (PMID 42253452, 2026). "This review delves into the mechanisms of podocyte injury in DKD, including the roles of mitochondrial dysfunction, lipid metabolism disorders, and the protective effects of key molecules such as ABCA1." (PMID 40862124, 2025). "This study demonstrated the crucial roles played by the miR-33-5p/ABCA1/CS axis in regulating cholesterol efflux, inflammation, apoptosis, and aging in VECs, and also suggested the axis as a target for managing lipid metabolism disorders." (PMID 34517822, 2021). "Furthermore, as MMP-9 has been shown to cleave citrate synthase ex vivo, the change and involvement of MMP-9 in lipid metabolism disorders should also be further investigated, along with the role played by the miR-33-5p/ABCA1/CS axis." (PMID 34517822, 2021). "Based on these findings, our results suggest that the abnormal expression of placental ABCA1 may induce lipid metabolism disorder in the placenta, which leads to the occurrence of SPD, and there may be two mechanisms by which ABCA1 affects the SPD risk." (PMID 28630870, 2017). "Ox-LDL can also downregulate ABCA1 and ABCG1 in THP-1 derived human macrophages resulting in lipid metabolism disorder in macrophages." (PMID 37021059, 2023). "et Zucc., can activate the activities of ABCA1, ABCG1, and ApoE with PGC-1α as the central target to inhibit lipid deposition in cells and improve lipid metabolism disorder in the kidney, thus preventing or delaying the occurrence and development of DN." (PMID 34485530, 2021). "By substantially upregulating the expression of circRNA_0001805, ABCA1 and CPT1, GA-RM/GZ/PL can release glycyrrhizic acid to reduce the inflammatory response and play a synergistic role to protect against NAFLD-induced lipid metabolism disorder." (PMID 34789275, 2021). "Abnormal expression of ABCA1 and ABCG1 in the placenta can elicit lipid metabolism disorder and adverse pregnancy outcomes." (PMID 28630870, 2017). "Collectively, our findings demonstrated that circRNA_0001805 inhibited NF-κB signaling cascades and promoted ABCA1/CPT1 expression in mice; these results corroborated the protective role of circRNA_0001805 against NAFLD-induced lipid metabolism disorder and hepatic inflammation in vivo." (PMID 34789275, 2021).
preeclampsia (10 papers, 2011 to 2025). Preeclampsia is a hypertensive disorder of pregnancy that is characterized by new-onset hypertension with proteinuria presenting after 20 weeks of gestation, and depending on mild or severe forms may initially present with severe headache, visual disturbances, and hyperreflexia. "Recently, it was shown that ABCA1 expression can be linked to disorders associated with abnormal placentation, such as preeclampsia." (PMID 36013052, 2022). "Moreover, the low expression of ABCA1 mRNA correlates with an increased risk of preeclampsia and other pregnancy complications." (PMID 36013052, 2022). "Differential ABCA1 expression in the placenta has been reported in primary antiphospholipid syndrome, preeclampsia, and spontaneous preterm deliveries." (PMID 34829614, 2021). "Some findings associated with preeclampsia in this study, such as MTHFR and RGS5 have been previously associated with preeclampsia, while maternal serum levels of TGFB2 and ABCA1 are altered in preeclampsia as well." (PMID 31557190, 2019). "However, in the placenta of preeclamptic women, expression of LXRA together with ABCA1 expression can be disturbed through hypoxia in early gestation complicated by preeclampsia and in consequence influence maternal-fetal cholesterol transport." (PMID 36013052, 2022). "In humans, fetal IUGR and maternal preeclampsia decrease Abca1 and Abcg1 expression." (PMID 29896121, 2018). "Furthermore, one study showed that serum ABCA1 could be detected in women with normal pregnancy, and the patients with preeclampsia had significantly lower serum ABCA1 levels than those in the control subjects." (PMID 34975757, 2021). "Therefore, both ABCA1 and ABCG1 are important to protect against toxic effects of oxysterols on placental and fetal development and placental function, thereby reducing the risks associated with pregnancy complications such as preeclampsia." (PMID 34829614, 2021). "One recent study revealed that the expression of NR1H3, NR1H2 and their target gene ABCA1 in JAR cells is stimulated under conditions of low oxygen concentration, mimicking the conditions occurring in preeclampsia." (PMID 22029530, 2011). "In our study, ABCA1 mRNA expression was increased in all trophoblast subpopulations and in BeWo b30 cells under hypoxia, whereas previous reports have described decreased apical ABCA1 protein expression in SCT during preeclampsia." (PMID 41446579, 2025). "Preeclampsia patients have elevated plasma CEC but lower ATP-Binding Cassette Subfamily A Member 1 (ABCA1)-mediated CEC, compared with plasma from normotensive pregnant females, which the authors postulate as a rescue mechanism in preeclampsia to mitigate lipid peroxidation." (PMID 38130330, 2023). "In EVT, preeclampsia induced pronounced changes in cholesterol transporter expression: ABCG1 was significantly downregulated (95th percentile CPM: Ctrl = 335.2; PE = 146.0, p = 3.60e-07), while ABCA1 showed a trend toward upregulation (95th percentile CPM: Ctrl = 261.4; PE = 528.2, p = 0.11)." (PMID 41446579, 2025). "In late-onset preeclampsia, the expression levels of LXRA, LXRB or ABCA1 were not significantly different from age-matched controls." (PMID 36013052, 2022).
thyroid cancer (9 papers, 2014 to 2025). "Moreover, although a recent study revealed an association between cholesterol and malignancy in thyroid cancer, the relationship between ABCA1 and TC remains unknown." (PMID 36672209, 2023). "These discoveries highlight the potential of ABCA1 as an important oncogene and a promising therapeutic target for the treatment of thyroid cancer (TC) with lung metastasis." (PMID 38791400, 2024). "Our RNA‐seq data from APOE‐overexpressing thyroid cancer cell lines showed increased expression of ABCA1, a cofactor in LXR activation, suggesting that APOE overexpression may induce LXR, thereby potentially rescuing impaired immunity in tumours." (PMID 39810624, 2025). "ABCA1-mediated EMT promotes thyroid carcinoma malignancy through the ERK/Fra-1/ZEB1 pathway." (PMID 40297807, 2025). "Further studies are needed to establish the role of ABCA1 on thyroid cancer." (PMID 31311983, 2019). "ABCA1 plays a role in regulating EMT through the ERK/FOSL1/ZEB1 pathway and has been identified as a new predictor of response to thyroid cancer with lung metastasis." (PMID 38791400, 2024). "In thyroid cancer, hsa_circ_0074817 targets miR-27a-3p, targeting MET, ABCA1, MMP13, and PLAG1, promoting cell proliferation, invasion, and metastasis in thyroid carcinoma." (PMID 34055888, 2021). "S1P is exported from mast cells via ABCC1, from astrocytes via ABCA1, from endothelial cells via ABCA1 and ABCC1, and from thyroid carcinoma cells via ABCC1." (PMID 28912626, 2017). "S1P has been shown to be exported from mast cells via ABCC1 (also known as multidrug resistant protein 1; MRP1), from astrocytes via ABCA1, from endothelial cells via ABCA1 and ABCC1, and from thyroid carcinoma cells via ABCC1." (PMID 25133174, 2014). "Similarly, the pathway involving ERK/Fra-1/ZEB1 is responsible for promoting thyroid cancer cell invasion and progression through EMT, facilitated by ABCA1." (PMID 37874419, 2023). "A recent study revealed that ABCA1 was upregulated in the most aggressive samples, although these changes were not substantial in advanced thyroid cancers, including poorly differentiated TC and anaplastic TC." (PMID 36672209, 2023).